DDX39B (DExD-box helicase 39B)
Description:
Involved in nuclear export of spliced and unspliced mRNA. Component of the TREX complex which is thought to couple mRNA transcription, processing and nuclear export, and specifically associates with spliced mRNA and not with unspliced pre-mRNA. The TREX complex is recruited to spliced mRNAs by a transcription-independent mechanism, binds to mRNA upstream of the exon-junction complex (EJC) and is recruited in a splicing- and cap-dependent manner to a region near the 5' end of the mRNA where it functions in mRNA export to the cytoplasm via the TAP/NXF1 pathway. The THOC1-THOC2-THOC3 core complex alone is sufficient to promote ATPase activity of DDX39B; in the complex THOC2 is the only component that directly interacts with DDX39B. Associates with SARNP/CIP29, which facilitates RNA binding of DDX39B and likely plays a role in mRNA export. May undergo several rounds of ATP hydrolysis during assembly of TREX to drive subsequent loading of components such as ALYREF/THOC4 and CHTOP onto mRNA. Also associates with pre-mRNA independent of ALYREF/THOC4. Involved in the nuclear export of intronless mRNA; the ATP-bound form is proposed to recruit export adapter ALYREF/THOC4 to intronless mRNA; its ATPase activity is cooperatively stimulated by RNA and ALYREF/THOC4 and ATP hydrolysis is thought to trigger the dissociation from RNA to allow the association of ALYREF/THOC4 and the NXF1-NXT1 heterodimer. Involved in transcription elongation and genome stability. Splice factor that is required for the first ATP-dependent step in spliceosome assembly and for the interaction of U2 snRNP with the branchpoint. Has both RNA-stimulated ATP binding/hydrolysis activity and ATP-dependent RNA unwinding activity. Even with the stimulation of RNA, the ATPase activity is weak. Can only hydrolyze ATP but not other NTPs. The RNA stimulation of ATPase activity does not have a strong preference for the sequence and length of the RNA. However, ssRNA stimulates the ATPase activity much more strongly than dsRNA. Can unwind 5' or 3' overhangs or blunt end RNA duplexes in vitro. The ATPase and helicase activities are not influenced by U2AF2; the effect of ALYREF/THOC4 is reported conflictingly with [PubMed:23299939] reporting a stimulatory effect. (Microbial infection) The TREX complex is essential for the export of Kaposi's sarcoma-associated herpesvirus (KSHV) intronless mRNAs and infectious virus production.
Synonyms: BAT1; UAP56; D6S81E
Tractability: Small molecule: a structure with a bound ligand is known. PROTAC: UniProt records ubiquitination sites on it; ubiquitination databases record sites on it; its protein half-life has been measured.
Target class: Enzyme; Hydrolase
Safety:
Unwanted effects reported when the protein is acted on. In parentheses: how it was acted on, where the effect was seen, and who reports it.
DRESS Syndrome or Stevens-Johnson Syndrome (source: ClinPGx)
Gene: Protein-coding gene on chromosome 6 (31,530,218 to 31,542,451, reverse strand). Ensembl gene ENSG00000198563.
Subcellular location: Nucleus; Nucleus speckle; Cytoplasm
Subcellular location (Human Protein Atlas): Nuclear speckles
Pathways (Reactome):
Metabolism of RNA: Transport of Mature mRNA derived from an Intron-Containing Transcript; mRNA 3'-end processing; mRNA Splicing - Major Pathway
Signal Transduction: RHOBTB2 GTPase cycle
Gene Ontology:
Molecular function: ATP hydrolysis activity; ATP-dependent activity, acting on RNA; ATP-dependent protein binding; identical protein binding; protein binding; RNA binding; RNA helicase activity; U4 snRNA binding; U6 snRNA binding; ATP binding; nucleic acid binding
Biological process: mRNA export from nucleus; mRNA splicing, via spliceosome; RNA splicing; spliceosomal complex assembly; RNA export from nucleus
Cellular component: cytoplasm; nuclear speck; nucleus; spliceosomal complex; transcription export complex; U4 snRNP; U6 snRNP; nucleoplasm
Genetic constraint (gnomAD): Loss-of-function variants: 5 observed, 47.99 expected, observed/expected ratio (o/e) 0.1, 90% interval 0.053 to 0.22. The upper end of that interval is the gene's LOEUF score, 0.22, which puts it in group 1 of 6, group 1 being the genes least tolerant of losing a copy. Missense variants: 180 observed, 569.71 expected, observed/expected ratio (o/e) 0.32, 90% interval 0.28 to 0.36. Synonymous variants: 173 observed, 207.56 expected, observed/expected ratio (o/e) 0.83, 90% interval 0.74 to 0.95.
Homologues: Orthologues: chimpanzee DDX39B (100% identical), macaque DDX39B (100% identical), guinea pig DDX39B (99% identical), pig DDX39B (99% identical), dog DDX39B (99% identical), mouse Ddx39b (99% identical), rabbit DDX39B (99% identical), rat Ddx39b (99% identical), tropical clawed frog ddx39b (94% identical), zebrafish ddx39b (94% identical). Paralogues in human: DDX39A (89% identical), EIF4A2 (34% identical), EIF4A1 (33% identical), EIF4A3 (32% identical), DDX3Y (31% identical), DDX3X (30% identical), DDX20 (30% identical), DDX19B (30% identical), DDX19A (29% identical), DDX6 (29% identical), DDX46 (29% identical), DDX49 (29% identical), and 26 more.
Diseases named in the same sentence as DDX39B in open-access papers:
DDX39B is named in the same sentence as 47 diseases in open-access papers, as found by Europe PMC text mining. Sharing a sentence is not in itself a finding about the gene and the disease. The quoted sentences say what the papers report.
colorectal cancer (7 papers, 2021 to 2025). A primary or metastatic malignant neoplasm that affects the colon or rectum. "Nevertheless, the underlying molecular mechanisms of DDX39B in the proliferation of human colorectal cancer (CRC) remain fairly elusive." (PMID 35046400, 2022). "Recently, we demonstrated that DEAD box helicase 39B (DDX39B) was upregulated and activated metabolic reprogramming in colorectal cancer and hepatocellular carcinoma." (PMID 40664668, 2025). "So these findings are consistent with the concept DDX39B can affect the proliferation of colorectal cancer in vitro and in vivo." (PMID 35046400, 2022). "In conclusion, DDX39B acts as a colorectal cancer promoter through its effect on the CDK6/CCND1, which can promote the G1/S phase transition to enhance CRC proliferation." (PMID 35046400, 2022). "This phenotype demonstrated that not only overexpression of DDX39B can promote the proliferation of the colorectal cancer cells but also that can be reversed after knockdown of the CDK6 and CCND1." (PMID 35046400, 2022). "Meanwhile, according to the TCGA datasets, we found the different expression levels of DDX39B in different colorectal cancer stages by UALCAN." (PMID 35046400, 2022). "And our study focused on the mechanism of DDX39B in the proliferation of colorectal cancer, we found that DDX39B can bind directly to the exons of CCND1/CDK6 mRNA to upregulate their expression and promote the CRC cell proliferation as an oncogene." (PMID 35046400, 2022). "The exact role and potential molecular mechanism of DDX39B in the progression of human colorectal cancer (CRC) remain to be investigated." (PMID 33436563, 2021). "DExD‐box helicase 39B (DDX39B) can promote colorectal cancer metastasis through activating the Warburg effect, which was confirmed as a poor prognostic indicator for the prognosis of colorectal cancer." (PMID 37864422, 2023). "However, recent studies have revealed that increased DDX39B could promote the tumour metastasis of colorectal cancer and enhance chemotherapy resistance in BRCA1-proficient ovarian cancers." (PMID 35141281, 2022). "In summary, this important finding further emphasized DDX39B can directly bind to its downstream CDK6 and CCND1 genes and upregulate their expression levels to promote the proliferation of the colorectal cancer cells." (PMID 35046400, 2022). "Recently, an increase in FUT3 regulated by DDX39B catalyzes the aberrant L-fucosylation of TGFβR-I, which enhances the DDX39B-mediated TGFβ/SMAD2 signaling pathway and finally facilitates the invasion and metastasis in the colorectal cancer development." (PMID 34485140, 2021).
ovarian carcinoma (6 papers, 2022 to 2024). A malignant neoplasm originating from the surface ovarian epithelium. "Moreover, inhibition of DDX39B triggers sensitivity of BRCA1-mutant ovarian cancer cells to chemotherapy drugs such as platinum and PARPi." (PMID 35832557, 2022).
melanoma (5 papers, 2020 to 2022). A malignant, usually aggressive tumor composed of atypical, neoplastic melanocytes. "We also evaluated the expression of DDX39B in primary and metastatic tumor tissues from melanoma, breast cancer, and prostate cancer patients." (PMID 35973989, 2022). "In melanoma cells it has been demonstrated that in hypoxic conditions, EV exhibit a miRNome and proteome signature (AKR7A2, DDX39B, EIF3C, FARSA, PRMT5, VARS), which is associated with poor prognosis for the patients." (PMID 34439311, 2021). "Hypoxic melanoma EVs carried a hypoxic signature consisting of six proteins (AKR7A2, DDX39B, EIF3C, FARSA, PRMT5, VARS) which were significantly associated with a poor prognosis for melanoma patients." (PMID 32183388, 2020). "Overexpression of DDX39B predicts poor prognosis and promotes aggressiveness of melanoma." (PMID 35004299, 2021). "Compared with primary lesions, DDX39B was augmented in metastatic prostate cancer tissues, but not in melanoma and breast cancer, suggesting that DDX39B may serve as a potential predictor of metastasis risk for certain cancers, including CRC and prostate cancer." (PMID 35973989, 2022).
breast carcinoma (4 papers, 2011 to 2024). "In order to observe the potential role of DDX39B in breast cancer, we performed GSEA enrichment analysis." (PMID 33020551, 2020). "In conclusion, this study found that DDX39B, EPHX2 (exo7), and HERC4 (exo23) can be used as potential targets for the treatment of breast cancer, which provides a new idea for the treatment of breast cancer." (PMID 33020551, 2020).
prostate carcinoma (4 papers, 2020 to 2024). A carcinoma that arises from epithelial cells of the prostate gland. "DDX39B was demonstrated to be an upstream regulator of AR-V7, indicating that it plays a critical role in regulating the progression of prostate cancer." (PMID 32489474, 2020). "For example, DDX39B is a potential therapeutic target in prostate cancer, and its expression imbalance may lead to multiple tumorigenesis events." (PMID 34445990, 2021).
COVID-19 (3 papers, 2022 to 2023). A disease caused by infection with severe acute respiratory syndrome coronavirus 2. "Our results showed that six spliceosomal component proteins (DDX5, DDX17, DDX39B, PRPF6, SNRNP40, and SNRNP200) were significantly down-regulated in COVID-19 patients." (PMID 35421082, 2022).
glioblastoma (3 papers, 2018 to 2020). The most malignant astrocytic tumor (WHO grade IV). "Loss of DDX39B has been reported to promote resistance to alkylating chemotherapy in glioblastoma cells." (PMID 33089952, 2020). "From a functional standpoint, loss of DDX39B promoted resistance to alkylating chemotherapy in glioblastoma cells." (PMID 32209106, 2020). "To test if the nucleolar localization of DDX49 was cell-type specific, we expressed GFP tagged DDX39B and DDX49 in other cell lines such as cervical cancer derived HeLa and glioblastoma derived U251MG." (PMID 29618122, 2018).
hepatocellular carcinoma (3 papers, 2024 to 2025). A malignant tumor that arises from hepatocytes. "This highlights the significant association of SFPQ, DDX39B, and UBAP2 with poor prognosis in hepatocellular carcinoma patients, underscoring their potential value as prognostic markers." (PMID 39133261, 2024). "DDX39B inhibits FBXW7-mediated ubiquitination and degradation of SREBP1, leading to increased lipid accumulation and promoting progression in hepatocellular carcinoma." (PMID 39944823, 2025). "This study systematically analyzed the complex relationship between paraspeckle genes, angiogenesis, and tumor immunity, determining that elevated expression of SFPQ, DDX39B, and UBAP2 is closely associated with poor prognosis in hepatocellular carcinoma (HCC) patients." (PMID 39133261, 2024).
influenza (3 papers, 2010 to 2022). An acute viral infection of the respiratory tract, occurring in isolated cases, in epidemics, or in pandemics; it is caused by serologically different strains of viruses (influenzaviruses) designated A, B, and C, has a 3-day incubation period, and usually lasts for 3 to 10 days. "Based on our data, we speculated that DDX39B and DDX39A may regulate influenza vRNP activity through their interaction with NP." (PMID 36084138, 2022).
viral infection (3 papers, 2018 to 2025). "A larger complex known as TREX, which performs important functions in many cellular events and viral infection, contains the THO complex, RNA helicase DDX39B, and mRNA export NXF/TAP-adaptor protein THOC4." (PMID 30769920, 2019).
autoimmune disease (2 papers, 2020 to 2024). A disorder resulting from loss of function or tissue destruction of an organ or multiple organs, arising from humoral or cellular immune responses of the individual to their own tissue constituents. "While the increase in inflammation induced by loss of DDX39B likely contributes to autoimmune disease, given the importance of NF-κB-mediated inflammation to therapy resistance, the increased inflammation seen with decreased DDX39B likely also underlies the resistance to chemotherapy." (PMID 32209106, 2020). "While these findings identify a pathway by which DDX39B promotes sensitization to DNA damaging therapy, the data also reveal a mechanism by which this helicase may act to mitigate autoimmune disease." (PMID 32209106, 2020). "Six genes in the MHC Class III region, DDX39B, DXO, LSM2, NELFE, PRRC2A, and SKIV2L, encode RBPs and have a well-defined role in post-transcriptional gene regulation and RNA monitoring, and these genes may have important functions in immunity and be associated with autoimmune diseases." (PMID 38770048, 2024).
autoimmune disorders (2 papers, 2023 to 2025). "Given the importance of FOXP3 in autoimmunity, this work cements DDX39B as an important guardian of immune tolerance." (PMID 37261960, 2023). "While this connection between DDX39B and autoimmunity was compelling, evolutionary arguments suggested that this RNA helicase would play other roles in immunity." (PMID 37261960, 2023). "Given that Tregs help limit T‐cell‐mediated autoimmunity, DDX39B may be important in preventing the development of a number of autoimmune disorders." (PMID 39620586, 2025).
Fanconi anemia (2 papers, 2021 to 2025). Fanconi anemia (FA) is a hereditary DNA repair disorder characterized by progressive pancytopenia with bone marrow failure, variable congenital malformations and predisposition to develop hematological or solid tumors. "This has been shown in artificial systems, and in yeast and human cells depleted of R-loop suppressor factors such as THO, Sin3A, Fanconi Anemia, Sen1/SETX, the UAP56/DDX39B helicase, or the bromodomain chromatin factor BRD45,11,12,22–24." (PMID 34294712, 2021).
Obesity (2 papers, 2026). Accumulation of substantial excess body fat. "Because mature adipocytes are the commonest cell type in adipose tissue, the contrasting finding from these studies suggests that obesity affects the expression of DDX39B differently in preadipocytes and mature adipocytes." (PMID 41077621, 2026). "Interestingly, in contrast to the reduced expression in the current study, a previous study found DDX39B to be upregulated in VAT preadipocytes from people with obesity." (PMID 41077621, 2026). "Lastly, our study identifies several differently regulated proteins whose role in obesity and adipose tissue is poorly known, such as ANXA8, DDX39B, STX7, SYNCRIP, SYNGR2, and PAK2." (PMID 41077621, 2026).
sarcoma (2 papers, 2020 to 2024). A usually aggressive malignant neoplasm of the soft tissue or bone. "In addition, DDX39B is a crucial contributor to Kaposi's sarcoma-associated herpesvirus intronless mRNA nuclear export and virus replication." (PMID 32084007, 2020). "In terms of gene signatures, an immune-related five-gene signature based on MYBL2, FBN2, TSPAN7, GCSH, and DDX39B is a prognostic biomarker for sarcoma patients." (PMID 38240704, 2024).
Alzheimer disease (1 paper, 2022). A progressive, neurodegenerative disease characterized by loss of function and death of nerve cells in several areas of the brain leading to loss of cognitive function such as memory and language. "Among candidate modifier genes involved in neurological development and functioning, at least four genes are closely related to Alzheimer’s disease including FIS1, DDX39B, PRND, GSTM3." (PMID 36553485, 2022).
chordoma (1 paper, 2023). Chordomas are rare malignant tumors arising from embryonic remnants of the notochord in axial skeleton. "Conversely, a small number of genes was identified whose gene dependency scores were of a greater magnitude in non-chordoma than in chordoma cell lines, and these genes included MED1, MRPS10, and DDX39B." (PMID 37024492, 2023).
clear cell carcinoma (1 paper, 2021). "DDX39B can also predict adverse efficacy of immune checkpoint therapy in clear cell carcinoma." (PMID 35004299, 2021).
colon adenocarcinoma (1 paper, 2022). "From the TCGA database, significant increases in DDX39B mRNA were observed in colon adenocarcinoma and rectal adenocarcinoma (READ) tissues compared with normal tissues." (PMID 35973989, 2022).
colon cancer (1 paper, 2022). "Consistent with our results, upregulated DDX39B protein expression was observed in the Clinical Proteomic Tumor Analysis Consortium colon cancer database." (PMID 35973989, 2022).
glioma (1 paper, 2023). A benign or malignant brain and spinal cord tumor that arises from glial cells (astrocytes, oligodendrocytes, ependymal cells). "Furthermore, the chromobox protein homolog 3 (CBX3), DEK proto-oncogene (DEK), and DEAD (Asp-Glu-Ala-Asp) box polypeptide 39B (DDX39B) transcripts and proteins were up-regulated in glioma versus normal brain tissues." (PMID 37762371, 2023).
head and neck cancer (1 paper, 2024). A primary or metastatic malignant neoplasm affecting the head and neck. "C4A, DDX39B, and MICA/B had associations with risk of head and neck cancers of which one, DDX39B, appeared cancer-subtype-specific and was associated with a lower risk of oropharyngeal cancer [OR: 0.24, 95% CI: 0.13 to 0.43; PP4: 0.94]." (PMID 38684708, 2024).
Hepatitis (1 paper, 2014). Inflammation of the liver. "Polymorphisms in DDX39B (BAT1) have been described in several diseases with inflammatory profiles, including neuropathy, myasthenia gravis, allergies, Alzheimer disease, myocardial infarction, hepatitis, rheumatoid arthritis, Chagas disease, among others." (PMID 25038626, 2014).
hyperuricemia (1 paper, 2018). An abnormally high level of uric acid. "Of these SNVs, nine are located at seven gene loci (DDX39B, NFKBIL1, CDC42BPG, CDC63, BRAP, ACAD10, and PCNX3) that might be novel susceptibility loci for hyperuricemia." (PMID 29124443, 2018).
leukemia (1 paper, 2025). A malignant (clonal) hematologic disorder, involving hematopoietic stem cells and characterized by the presence of primitive or atypical myeloid or lymphoid cells in the bone marrow and the blood. "A half of these proteins have no reported relationship with leukemia, i.e., LTB4R2, DDX39B, ZNF668, ZNF788, and DXO." (PMID 40699783, 2025).
lymph node metastasis (1 paper, 2025). "According to the clinicopathologic features, DDX39B expression was associated with lymph node metastasis, M stage, and TNM stage in NSCLC patients." (PMID 40664668, 2025). "Moreover, elevated DDX39B protein was observed in primary NSCLC tissues of patients with lymph node metastasis compared with those without lymph node metastasis." (PMID 40664668, 2025).